KRAS (KRas proto-oncogene, GTPase)
Diseases named in the same sentence as KRAS in open-access papers (continued):
Sharing a sentence is not in itself a finding about the gene and the disease.
colon adenocarcinoma (62 papers, 2011 to 2026). "KRAS, according to TCGA, is the fourth mutation gene in colon adenocarcinomas (CAs) at a frequency of 37%, with missense as the leading mutation type." (PMID 35774610, 2022). "Depending on the status of KRAS mutation, the samples of colon adenocarcinomas were divided into two subgroups." (PMID 35774610, 2022). "In colonic adenocarcinomas with the KRAS mutation, nuclei were moderately stained with a weak to negatively stained cytoplasm." (PMID 34201061, 2021). "Our data revealed a downregulation of MKNK2a and an upregulation of MKNK2b in colon adenocarcinomas, which is closely correlated with KRAS mutation." (PMID 33602301, 2021). "To investigate the effects of destabilization of β-catenin and RAS on CSC activation related to metastasis, we subcutaneously implanted NOD/SCID mice with KRAS mutated colon adenocarcinoma metastasized to lung, and measured effect of KYA1797K treatment." (PMID 32143715, 2020). "In the second patient, who incidentally exhibited a higher level of the mutant KRAS allele, a lung metastasis from a colon adenocarcinoma was diagnosed 3 years later." (PMID 32441866, 2020). "There are currently 209 CRCs with KRAS mutations, which include 176 colon adenocarcinomas and 33 rectal adenocarcinomas." (PMID 31729406, 2019). "A 52-year-old woman was diagnosed with stage IV KRAS G12C mutated rectosigmoid colonic adenocarcinoma involving the liver and was started on treatment with capecitabine, oxaliplatin, and bevacizumab." (PMID 30923702, 2019). "Words used in radiology reports, which have direct implications on disease course, tumor burden, and therapy, appear with differing frequency in patients with KRAS mutations versus wild-type colon adenocarcinoma." (PMID 28869500, 2017). "For colon adenocarcinoma, extracting genotype from imaging data is extremely promising, as the presence of a KRAS mutation greatly alters the treatment plan for patients." (PMID 28869500, 2017). "Lung and colon adenocarcinomas show KRAS mutations in a subset of tumors, particularly in codon 12 and 13, and these tumors harboring KRAS mutation are associated with resistance to anti-EGFR directed therapeutic approaches." (PMID 26053092, 2015). "The analysis of the histological type revealed that KRAS mutation was mainly associated with colon adenocarcinoma NOS, as it was detected in 50 of 54 tumours with mutated genotype included in the study (92.6%), while the other four tumours (7.4%) were diagnosed as mucinous type." (PMID 39996841, 2025). "Moreover, further molecular genetic work-up revealed that both small intestinal and colon adenocarcinomas harbored an identical missense mutation (p.G12D) of KRAS gene." (PMID 32867793, 2020). "This is evidenced by the recent finding that BRAF V600E and KRAS G13D mutations in colon adenocarcinoma upregulate the transcription factors MAFG and ZNF304, respectively, resulting in targeted promoter CGI hypermethylation near the MAFG and ZNF304 binding sites." (PMID 32327612, 2020). "KRAS G12D is the most prevalent somatic mutation detected in colonic adenocarcinomas." (PMID 28755461, 2017). "Using systemically delivered siRNAs, KRAS as a target of KRAS siRNA was silenced which regulated cellular proliferation and survival in lung and colon adenocarcinoma treatment." (PMID 34675807, 2021). "In particular, 45 adenocarcinomas (41 colon, 2 lung, 2 pancreas) exhibited co-occurring KRAS and PIK3CA mutations; two colon adenocarcinomas had concomitant BRAF and PIK3CA mutations." (PMID 26435479, 2015).
colon adenocarcinoma (continued). "A similar and robust association was observed in colon adenocarcinoma (COAD) cohort (p = 1.9 × 10−9), reinforcing the hypothesis of a conserved regulatory relationship between KRAS activation and KCNN4 expression across epithelial malignancies." (PMID 40952239, 2025). "Lastly, we show primary colon adenocarcinoma patient samples with R117fs and G659fs variants have transcriptional profiles similar to BRAF missense mutations with activated RAS/MAPK signaling, consistent with KRAS signaling pathways being GOF in both variants." (PMID 34214079, 2021). "The comparison of exosomal proteome between KRAS wild type DKS-8 cells of human colon adenocarcinoma cells DLD-1 and K-RAS mutant type DKO-1 cells indicated that DKS-8 secreted by DKO-1 exosomes was not only significantly proliferated but its invasion capacity was also increased." (PMID 28851367, 2017). "The KRAS and BRAF V600E mutation rates detected in our series by both Sanger sequencing and ASLNAqPCR are compatible with the data reported in the literature for colon adenocarcinoma and the other tumors analyzed." (PMID 22558339, 2012). "We analyzed the correlation between KRAS mutational status and expression of several autophagy genes, including MAP1LC3B, ATG5, ATG10, ATG13, and ATG14 in both COAD (colon adenocarcinoma) READ (rectum adenocarcinoma) as well as normal tissue." (PMID 39057088, 2024). "Importantly, we detected significantly stronger nuclear and, in particular, cytoplasmic staining of phospho-NPM1 (Thr199) in tumor tissue specimens from BRAFV600E-mutated in comparison with KRAS mutant/BRAF wild-type and double wild-type KRAS/BRAF colonic adenocarcinomas using immunohistochemistry." (PMID 34201061, 2021). "Various potential biomarkers have been found in colon adenocarcinoma (COAD) patients receiving immunotherapy, such as microsatellite instability (MSI), programmed cell death-ligand 1 (PD-L1) expression, tumor mutation burden (TMB) and BRAF and KRAS gene mutation status." (PMID 34367132, 2021). "EEF1A1 expression has been determined to be independent of KRAS mutations in our study, suggesting that the expression of EEF1A1 is unlikely to involve KRAS-related colon adenocarcinoma." (PMID 31703307, 2019).
RASopathies (62 papers, 2013 to 2026). "An expanded RASopathy panel identified a previously reported pathogenic missense variant in KRAS (c.101C>G, p.Pro34Arg)." (PMID 37774117, 2024). "This study confirms the continuum of mosaic neurocutaneous RASopathies showing codon 146 KRAS variants in an individual with OES and, for the first time, in an individual with (isolated) epidermal nevus." (PMID 35409398, 2022). "Caitlin Chang, MD, presented a series of clinical cases of patients that had been diagnosed with mosaic RASopathies driven by KRAS mutations." (PMID 35266292, 2022). "Found in perhaps 1:1000 new births, RASopathies are associated with variants in genes encoding multiple RAS pathway components including KRAS, NRAS, BRAF, RAF1, and SHP2." (PMID 33855281, 2021). "In this study, we used a strong G12V KRAS mutation to mimic severe cases of RASopathies caused by strong KRAS mutations such as G12S to investigate the cellular mechanisms of cognitive deficits in these RASopathies." (PMID 33082413, 2020). "Our findings would contribute to understanding the physiological roles of KRAS as well as the pathophysiology of KRAS-associated RASopathies." (PMID 33082413, 2020). "RASopathy-associated KRAS mutations are gain-of-function mutations, but most of these mutant proteins have a milder activity than those with oncogenic mutations." (PMID 33082413, 2020). "Our study allowed the expansion of the clinical spectrum of mosaic RASopathies and supports that mosaicism for recurrent mutations in KRAS and FGFR1 is a commonly involved mechanism in these rare oculocutaneous anomalies." (PMID 30891959, 2019). "Our study allowed the expansion of the clinical spectrum of mosaic RASopathies and supports that somatic mosaicism for recurrent mutations in KRAS and FGFR1 is a commonly involved mechanism in these rare oculocutaneous developmental anomalies." (PMID 30891959, 2019). "RASopathy panel identified pathogenic missense variant in KRAS gene (c.173C>T, p.Thr58Ile)." (PMID 37774117, 2024). "RASopathies represent a family of mostly autosomal dominant diseases that are caused by missense variants in the rat sarcoma viral oncogene/mitogen activated protein kinase (RAS/MAPK) pathway including KRAS, NRAS, BRAF, RAF1, and SHP2." (PMID 33855281, 2021). "In addition, a distinct spectrum of germline KRAS mutations causes developmental disorders called RASopathies." (PMID 32990679, 2020). "This and a similar dominant inhibitory KRAS Gly60Arg mutation suggest that suppression of growth factor signaling rather than constitutively elevated ERK activity might contribute to RASopathy." (PMID 28002430, 2016). "Moreover mutation of KRAS residues 58–65 have been reported to increase RAS-MAPK signaling in patients with RASopathies." (PMID 28002430, 2016). "However, for reasons that remain unclear, KRAS is far more frequently mutated than the other Ras isoforms in cancer and RASopathies." (PMID 36864243, 2023). "The KRAS c.35G>A, p.(Gly12Asp) variant leads to constitutive overactivation and increased signal transduction into downstream pathways and is associated with overgrowth including various types of congenital nevi and vascular malformations (so-called mosaic RASopathies)." (PMID 36636551, 2022). "The affected residues (p.Gly23, p.Thr68, p.Gln71) exhibit high evolutionary conservation across RAS family GTPases associated with RASopathies, including HRAS, NRAS, KRAS, and RRAS2." (PMID 41517739, 2026).
RASopathies (continued). "Many of the RASopathy-associated genes are in gene families: RAF (BRAF and RAF1), RAS (HRAS, KRAS, MRAS, NRAS, RIT1, and RRAS2), MAP2K (MAP2K1 and MAP2K2), and SOS (SOS1 and SOS2)." (PMID 40496714, 2025). "In a review of patients with mosaic RASopathies including ECCL, the majority of ECCL patients had mutations in the KRAS gene, with one patient presenting with an NRAS gene." (PMID 41283481, 2025). "These included 2 subjects with multiple sclerosis, 1 subject with systemic lupus erythematosus, 1 subject with diploid-triploid mosaicism, 1 subject with mosaic KRAS-related RASopathy, and 1 subject with Myoclonic epilepsy with ragged-red fibers (MERRF)." (PMID 39333051, 2025). "Intriguingly, the RAC1P29S variant induced RASopathy-like manifestations in zebrafish akin to activated BRAF and KRAS, mitigated by PAK and MEK inhibitors." (PMID 38672195, 2024). "Our data identifies the concomitant ablation of HRAS and NRAS as a new molecular alteration capable of triggering the development of RASopathy phenotypes in mice through a mechanism involving the hyperactivation of KRAS-dependent signaling." (PMID 38886790, 2024). "NS is the most common type of RASopathy, and is a rare genetically heterogeneous autosomal dominant disorder caused by mutations in either the PTPN11, SOS 1, KRAS, BRAF or RAF1 genes." (PMID 37106005, 2023). "Expressing human RASopathy isoforms of KRAS, HRAS, RAF1, BRAF, and PTPN11 in Drosophila, we report important differences between disease isoforms including distinct signaling pathways and drug responses." (PMID 33855281, 2021). "Seven of eight patients were characterized by NGS, and in all of them mutations of RASopathy genes were detected (NRAS 4, KRAS 1, CBL 1, PTPN11 1)." (PMID 32344757, 2020). "Postzygotic KRAS, HRAS, NRAS, and FGFR1 mutations result in a group of mosaic RASopathies characterized by related developmental anomalies in eye, skin, heart, and brain." (PMID 30891959, 2019). "This syndrome can be considered a mosaic RASopathy because it is caused by postzygotic pathogenic variants in HRAS (HRas Proto-Oncogene, GTPase), KRAS (KRAS Proto-Oncogene, GTPase), or the NRAS (NRas Proto-Oncogene, GTPase) genes." (PMID 29552546, 2018). "Further, we compared the specific variants observed here to variants in HRAS, KRAS, or NRAS previously reported as pathogenic for RASopathies." (PMID 30500825, 2018). "Cardio-facio-cutaneous syndrome (CFC) is a rare RASopathy associated with mutations in BRAF, KRAS, MEK1 (MAP2K1) and MEK2 (MAP2K2)." (PMID 29590634, 2018). "Here we report, a syndromic familial case of a 12p duplication encompassing the dosage sensitive gene KRAS, whose phenotype overlapped with rasopathies." (PMID 27450488, 2016). "Some of these genes increase predisposition to cancer, for example, in rasopathies, and BRAF, KRAS, HRAS, NF1, NRAS PTPN11, RAF129." (PMID 27080396, 2016). "Additionally, co-occurring PVs in other RASopathies-associated genes were noted in eight cases, including seven with PTPN11 PVs and one with a KRAS PV." (PMID 40289159, 2025). "The biochemical relationship between the RASopathy proteins KRAS, RIT1 and LZTR1 was tested in zebrafish and fruit flies; all LZTR1 orthologs preferentially interacted with RIT1 orthologs, indicating that this interaction is also conserved in less-complex model organisms." (PMID 38672195, 2024). "The RASopathies, collectively, are a spectrum of genetic syndromes caused by mutations in genes involved in the RAS/ mitogen-activated protein kinase (MAPK) pathway, including but not limited to PTPN11, NRAS, KRAS, HRAS, BRAF, and MAP2K1." (PMID 39385823, 2024). "A distinct class of germline KRAS and NRAS mutations causes Rasopathy developmental disorders." (PMID 37681415, 2023). "Conversely, BI 2825, a preclinical tool compound that inhibits KRAS regardless of a particular mutation, represents an exciting potential therapeutic for RASopathy patients." (PMID 35178568, 2022).
RASopathies (continued). "Interestingly, in addition to patients with KRAS, NRAS, and BRAF mutations, we found that MM exhibited a long tail of alterations in rare, congenital RAS-pathway-related diseases, known as the “Rasopathies”." (PMID 35768438, 2022). "BI 1701963, which inhibits the interaction between RAS and SOS1 to inhibit RAS activation, is in clinical development for solid tumors harboring a KRAS mutation, but it also represents a potential RASopathy therapeutic, although it has not yet been tested in RASopathy models." (PMID 35178568, 2022). "For example, RASopathies, such asNoonan syndrome, Neurofibromatosis 1 and Leopard syndrome, are a subtype ofdevelopmental diseases characterized by mutations in genes encoding for components ofthe Ras/MAPK pathway (NF1, PTPN1, SOS1, RAF1,KRAS, NRAS, SHOC2, CBL)." (PMID 29719609, 2018). "The relatively high incidence of the most frequent mosaic RASopathy; sebaceous nevi (1 in 1,000 births) suggest that KRAS mutations present at a mosaic state in humans may not be a rare phenomenon." (PMID 27705932, 2016). "More than 90% of JMML cases harbor germline or somatic mutations in one of five canonical driver genes-PTPN11, NRAS, KRAS, NF1, or CBL-establishing JMML as the prototypical malignant manifestation of RASopathy biology." (PMID 42193013, 2026). "Lastly, RASopathies, particularly those involving the KRAS gene (Kirsten rat sarcoma viral oncogene homolog), seem to play an important role in the development of MS." (PMID 40426812, 2025). "Multigene panel for common RASopathy genes that includes BRAF, MAP2K1, MAP2K2, KRAS and YWHAZ usually detects up to 90% of individuals with CFC and it is the preferred initial test." (PMID 38136934, 2023). "Because of their functional significance RAS signaling pathway components including NRAS, KRAS, NF-1, PTPN11, and CBL were summarized as RASopathy genes within one category." (PMID 32344757, 2020). "In addition to the well-characterized NRAS, KRAS, and BRAF genes, our study revealed that the germline Rasopathy genes represent a long tail of somatic alterations linking MM to these rare, congenital RAS-pathway-related diseases." (PMID 35768438, 2022). "Mechanistically, the increased levels of activated KRAS-GTP and pERK detected in various biological samples including MEFs, heart tissue, or isolated blood platelets, appear to be the main driving force behind the various RASopathy-like phenotypes displayed by our HRAS/NRASDKO mice." (PMID 38886790, 2024). "A KRAS p.Q61R mutation was found in both the affected and unaffected bone of one MAP2K1 mutation-negative patient with skin lesions consistent with RASopathy, who likely has melorheostosis as part of a more complex early embryonic mosaic RASopathy, which will be reported separately." (PMID 29643386, 2018).